ACE (angiotensin I converting enzyme)
Diseases named in the same sentence as ACE in open-access papers (continued):
Sharing a sentence is not in itself a finding about the gene and the disease.
Obesity (continued). "Therefore, this study was investigated whether the ACE I/D polymorphism affects the susceptibility of Korean adults to develop obesity, regardless of sex or age." (PMID 32408411, 2020). "In DD genotype carriers, a significant association was found between insulin resistance and obesity as presented by BMI, WC and WHtR, although the variations in percentages between DD and I-carriers were not high enough to conclude a clear effect of ACE I/D on such an association." (PMID 27777603, 2016). "While ANG II isassociated with obesity, oxidative stress and insulin resistance, ACE 2/ANG 1–7 axis hasemerged as a beneficial antagonist of ACE/ANG II axis, which improves systemic insulinsensitivity, glucose homeostasis and body weight." (PMID 27487419, 2016). "In Korean children, the best combination to predict obesity was SLC12 A3, ACE and GRK4 A486V in boys, and CYP11β-2 and GRK4 A486V in girls as sodium intake was increased." (PMID 25768006, 2015). "Animal models with systemic deletion of RAS components (Agt, renin, ACE, AT1a, and AT2) were protected from diet-induced obesity and metabolic disorders." (PMID 23483012, 2013). "The present study compared RAS blockers, including a direct renin inhibitor, an ACE inhibitor and an AT1R antagonist, in a mice model of diet-induced obesity and insulin resistance." (PMID 23894285, 2013). "Angiotensinogen, renin (or peptides with renin-like activity), angiotensin converting enzyme (ACE), and AT1 and AT2 receptors are all secretory products of the rodent adipocyte, and the expression of some are increased in obesity." (PMID 22475205, 2012). "The Angiotensin-converting enzyme (ACE) has a role in blood pressure regulation via the renin-angiotensin-aldosterone system (RAAS), in fertility, immunity, hematopoiesis, and diseases such as obesity, fibrosis, and Alzheimer’s dementia." (PMID 35571459, 2022). "The synthetized peptides exhibited in vitro antioxidant activity through radical scavenging, ACE inhibitory activity, anti-diabetic effects through inhibition of α-amylase, α-glucosidase, and DPP-IV, and/or obesity modulatory ability by inhibition of pancreatic lipase." (PMID 36358473, 2022). "The frequencies of ACE DD genotypes were 41.7 and 40.8%, respectively, in hypertensive cases and normotensive controls regardless of obesity and T2DM status." (PMID 26491214, 2015). "The present study aimed to compare the effect of blockades, using a direct renin inhibitor, an ACE inhibitor, and an AT1R antagonist, at different points in the RAS on glucose intolerance and pancreatic injury in a mice model of insulin resistance and obesity." (PMID 23894285, 2013). "Despite the unchanged ACE and lower systemic Ang II levels in obesity, the cardiac RAS was increased in OZR and EXT in obese Zucker rats reduced some of the cardiac RAS components and prevented obesity-related CH." (PMID 23077501, 2012). "Furthermore there was no significant change in the mRNA expression over 48 hours of CD14, endothelin-1 or ACE while there was a marked decrease in FABP-4, GPX-3, and LPL mRNA but enhanced release in obesity." (PMID 20508843, 2010). "Besides, two genes (ACE I/D and MTHFR C677T) polymorphisms are not found to have any influence on obesity." (PMID 34414818, 2021). "However, our data indicate that inflammatory markers in ACE inhibitor-treated animals are lower prior to a reduction in leptin expression, suggesting that leptin is not the principal factor in inflammation in obesity and its reduction by ACE inhibition." (PMID 34149621, 2021). "Angiotensin converting enzyme (ACE) is well-known for its role in blood pressure regulation via the renin–angiotensin aldosterone system (RAAS) but also functions in fertility, immunity, haematopoiesis and diseases such as obesity, fibrosis and Alzheimer’s dementia." (PMID 33146371, 2020).
Obesity (continued). "We were not able to find any associations between BMI and WC (overweight/obesity) and ACE and AGT polymorphisms, indicating that the RAS system might not be involved in overweight and obesity, at least based on genetic backgrounds." (PMID 31365628, 2019). "For example, boys with GRK4 A486V, ACE, and SLC12A3 mutants and girls with GRK4 A486V hetero and CYP11β-2 mutant may reduce their daily sodium intake as if they want to reduce the prevalence of obesity." (PMID 25768006, 2015). "Here, we investigated the potential anti-obesity and anti-hypertensive effects of DHSGT using a high-fat diet-induced mouse model and in vitro assays to evaluate possible DHSGT inhibition of pancreatic lipase and angiotensin-1-converting enzyme (ACE) activities." (PMID 25280587, 2014). "Another possible reason for the lack of arterial pressure reduction to an ACE inhibitor in the SSLepRmutant strain is the impact of other obesity-related mediators (i.e., endothelin, 20-HETE, and catecholamines) that could contribute to the maintenance of arterial pressure." (PMID 34975523, 2021). "Thus we speculate that the role of ACE in obesity development and weight regain touches a complex network, not only involving adipose tissue development, but also water and sodium retention, and possibly satiety hormone regulation to control energy intake." (PMID 21340022, 2011). "Inflammatory adipokines [IL-6, IL-10, ACE, TGFβ1, TNFα, IL-1β, PAI-1, and IL-8] plus one anti-inflammatory [IL-10] adipokine were identified whose circulating levels as well as in vitro release by fat are enhanced in obesity and are primarily released by the nonfat cells of human adipose tissue." (PMID 20508843, 2010).
diabetic nephropathy (231 papers, 2006 to 2026). "The ACE inhibitor captopril was first shown in 1993 to slow diabetic nephropathy progression in type 1 diabetes, halving the risk of doubling serum creatinine." (PMID 40563449, 2025). "The influence of genetic factors, including two ACE polymorphisms, on an increased risk of developing diabetic nephropathy or an increased likelihood of renal replacement therapy due to ongoing diabetic nephropathy has been investigated." (PMID 38398308, 2024). "In this study, logistic regression was used to assess the risk of developing diabetic nephropathy or the likelihood of renal replacement therapy based on ACE polymorphisms." (PMID 38398308, 2024). "The aim of this study was to assess the role of selected ACE polymorphisms (rs4343 and rs4646994) in the risk of development of diabetic nephropathy and in the likelihood of renal replacement therapy." (PMID 38398308, 2024). "In conclusion, the study reveals significant associations between one of the ACE polymorphisms (rs4343) and the risk of diabetic nephropathy or the likelihood of renal replacement therapy." (PMID 38398308, 2024). "Based on the discussion above it is evident that there was a need to explore polymorphism in more genes related to renal function like GLO-1, CBR-1, and ACE, and look for any association with the development of early severe diabetic nephropathy." (PMID 38545031, 2024). "For example, specific polymorphisms in genes associated with glucose metabolism, such as the ACE gene, have been linked to an elevated susceptibility to diabetic nephropathy." (PMID 37868469, 2023). "ACE insertion/deletion polymorphism is also associated with diabetic kidney disease, the frequency of DD and ID genotype distribution being higher compared with non-diabetic kidney disease cohorts, leading to functional decline." (PMID 32901433, 2021). "But, genetic variation in ACE level has been well-established as a risk factor for diabetic nephropathy, in type 1 diabetes." (PMID 31316987, 2019). "Mooyart and coworkers’ meta-analysis found 42 studies of ACE, giving an overall odds ratio for diabetic nephropathy of 1.24 (95% CI 1.12–1.37), for the deletion (D allele), but comment that the effects are more marked in Asian than European populations." (PMID 27871254, 2016). "Population studies have shown an association between diabetic nephropathy (DN) and insertion/deletion (I/D) polymorphism of the angiotensin-converting enzyme (ACE) gene (ACE in humans, Ace in mice)." (PMID 26442284, 2015). "It has been demonstrated that D allele (Deletion; deleted sequence) was related to increased serum level of ACE enzyme, however, I allele (addition; insertion) had the opposite role, and individuals with I/I genotype is developed less to diabetic nephropathy." (PMID 26311652, 2015). "Another protein associated with diabetic nephropathy is angiotensin I-converting enzyme (ACE), elevated levels of which are found in this pathology." (PMID 25988147, 2014). "They conducted a comprehensive meta-analysis on 63 published studies from 1994 to 2010 with 14,108 cases and 12,472 controls relating variants of the ACE I/D polymorphism to the risk of developing diabetic nephropathy." (PMID 25587546, 2014). "While the initial study found a protective effect of the II genotype on the development of nephropathy in IDDM patients, subsequent studies have addressed the role of ACE I/D polymorphism in the development and progression of diabetic nephropathy." (PMID 25587546, 2014). "Despite the large amount of studies looking for candidate genes, the ACE I/D polymorphism remains the unique and well-characterized locus clearly associated with development and progression of diabetic nephropathy." (PMID 25587546, 2014). "Up to now, the I/D polymorphism of ACE gene is the most extensively studied marker for association with diabetic nephropathy." (PMID 25587546, 2014).
diabetic nephropathy (continued). "Female gender was also associated with higher urinary ACE mRNA levels, as was albuminuria, the latter being in agreement with studies in patients with diabetic nephropathy." (PMID 22629438, 2012). "The ACE D allele was associated with increased risk of diabetic nephropathy (OR[95%CI]=1.24 [1.12-1.37])." (PMID 23049672, 2011). "A meta-analysis of 42 studies including 13,000 participants (published between 1994 and 2010) reported an association between the ACE I/D polymorphism and diabetic nephropathy." (PMID 23049672, 2011). "Wide inter-ethnic allelic variations of the Angiotensin Converting Enzyme (ACE) i nsertion-deletion (I/D) gene polymorphism were thought to be responsible for the conflicting gene–diabetic nephropathy disease association worldwide." (PMID 21031056, 2010). "A number of meta-analyses have been conducted to clarify the role of ethnicity on the association of ACE gene polymorphism with diabetic nephropathy." (PMID 21031056, 2010). "We have investigated the genetic susceptibility of the ACE gene to diabetic nephropathy in the multiethnic Malaysian population." (PMID 21031056, 2010). "In our study, a statistically significant relationship was observed between the D allele, DD genotype of the ACE polymorphism and diabetic nephropathy in South Indian type II diabetic nephropathy patients." (PMID 20535249, 2009). "Of all the markers tested for association with diabetic kidney disease, ins/del polymorphisms in ACE and Met235Thr SNP in AGT genes are the two most extensively studied." (PMID 16672053, 2006). "Although most of the studies on ACE I/D polymorphism have been very encouraging with regard to the role of DD genotype in the pathophysiology and treatment of diabetic nephropathies." (PMID 17042963, 2006). "The only other published study on ACE ins/del polymorphism in diabetic nephropathy subjects from India showed a significant association of the del allele." (PMID 16672053, 2006). "Some of the ACE polymorphisms that may be associated with the development of diabetic nephropathy are rs4343 and rs4646994." (PMID 38398308, 2024). "Although there are indications that identify ACE polymorphisms as one of the risk factors in kidney transplant rejection, there are no studies that would confirm their role in the development of diabetic nephropathy that leads to transplantation." (PMID 38398308, 2024). "The ACE I/D polymorphism has been associated with conditions like vitiligo, different cancers, infertility and loss of pregnancies, cerebrovascular accidents, diabetic nephropathy and other renal disease, and cardiovascular complications." (PMID 37284379, 2023). "Due to an already existing elevated regulation of enzyme ACE and reduced regulation of enzyme ACE-2, patients with chronic illnesses of the kidney, particularly those suffering from diabetic nephropathy, may be at an increased risk of developing AKI." (PMID 36237801, 2022). "Additionally, ACE I/D polymorphism has been previously associated with the development of diabetic nephropathy, while the ACE II genotype is believed to be nephroprotective in T1DM and T2DM16." (PMID 35610262, 2022). "Evaluating the ACE I/D polymorphism in diabetic nephropathy is a reliable tool to identify diabetic patients at risk and identify patients who may benefit from antiproteinuric (renoprotective) therapy with ACE inhibitors and/or ARBs." (PMID 25587546, 2014). "We suggested that the ACE DD genotype might be a significant risk factor for the progression of diabetic nephropathy." (PMID 25587546, 2014). "Although diabetic nephropathy is caused by a different pathomechanism affecting primarily glomerular capillaries, it is clear from large trials that renal outcome is improved when treating patients with ACE inhibitors." (PMID 23446441, 2013). "Therefore, our current study provides a novel finding demonstrating a null association between ACE I/D gene polymorphism and diabetic nephropathy, with regard to the Malay ethnic group." (PMID 21031056, 2010).
diabetic nephropathy (continued). "A more stringent case definition of diabetic nephropathy and a larger sample size to elucidate the association of ACE I/D gene polymorphism on diabetic nephropathy in the Chinese ethnic group in Malaysia may be necessary." (PMID 21031056, 2010). "Polymorphisms in genes encoding PPAR-γ, eNOS, GLUT-1, aldose reductase, MTHFR, apo-E and components of the renin-angiotensin system (RAS) including angiotensinogen, Ang-II receptor type 1, and particularly, the ACE gene, have been implicated in the pathogenesis of diabetic nephropathy." (PMID 21031056, 2010). "Early detection of diabetic nephropathy, adoption of multifactorial interventions targeting its main risk factors and the use of renal-protective agents such as ACE inhibitors might reduce the progression of renal disease." (PMID 18230135, 2008). "What is more, ACE polymorphisms may play a role in the development of diabetic nephropathy." (PMID 38398308, 2024). "In addition, extended studies could take into account the impact of selected ACE polymorphisms on the development of diabetic nephropathy by assessing the progression of renal failure using the speed of the decline of eGFR." (PMID 38398308, 2024). "In subgroup analyses of diabetic nephropathy, study design (OR for moderate effect: 1.21; 95% CI: 1.02–1.42) and body mass index (OR of moderate effect: 0.84; 95% CI: 0.70–1.00) had significant moderate effects on ACE I/D polymorphisms and diabetic nephropathy." (PMID 24498151, 2014). "First, this is the largest trial evaluating the association of the ACE/ID polymorphism on renal outcome and death during angiotensin II-receptor blockade in diabetic nephropathy; the study may well be underpowered in relation to the individual components of composite endpoint." (PMID 25587546, 2014). "The primary objective of the study was to find the pattern of distribution of ACE gene polymorphism in healthy controls, in type II DM without nephropathy, type II DM with nephropathy and to study the relation between DD gene polymorphism and diabetic nephropathy." (PMID 20535249, 2009). "While existing treatments primarily focus on hemodynamic modifications through ACE inhibitors, ARBs, and SGLT2 inhibitors, M-SYFSY directly targets the metabolic dysfunction underlying diabetic kidney disease pathogenesis." (PMID 41508092, 2026). "Actually, the first demonstration of nephroprotective effect of ACE inhibitors (in 1993) was limited to the case of diabetic nephropathy." (PMID 40004772, 2025). "It was only four years later, in 1997, that ACE inhibitors were shown to work in non-diabetic nephropathies, the same dynamic of discovery occurring nowadays with SGLT2i." (PMID 40004772, 2025). "The heterozygous ACE genotype (ID) has previously been linked to LOS responsiveness in diabetic nephropathy, and our results highlight a novel interaction between LOS usage and ACE genotype in CAF levels." (PMID 40464208, 2025). "Emerging evidence points to the importance of the role played by the ACE molecule in the pathogenesis of diabetic nephropathy." (PMID 38398308, 2024). "The molecular docking analysis was performed to calculate the binding affinity between the N and C domains of ACE and their ligands—drugs from the ACEi group, which are used in the treatment of diabetic nephropathy." (PMID 38398308, 2024). "Higher ACE concentrations were observed in patients with diabetic nephropathy (p = 0.012) and in patients with diabetic nephropathy after kidney transplantation (p = 0.005) compared to the control group." (PMID 38398308, 2024). "ACE inhibitors (ACEi) are widely used as standard therapy in patients with diabetic nephropathy due to their reported renal protective effects." (PMID 38398308, 2024). "ACE inhibitors have a proven efficacy in diabetic kidney disease and are the first-line drugs in diabetic nephropathy even in normotensive patients, further highlighting the gene’s role in DN pathogenesis." (PMID 39336582, 2024).